CD44 (CD44 molecule (IN blood group))
Diseases named in the same sentence as CD44 in open-access papers (continued):
Sharing a sentence is not in itself a finding about the gene and the disease.
ovarian carcinoma (continued). "Moreover, in vitro and in vivo experiments showed increased CSC properties and enhanced glycolysis of cell subpopulations isolated based on tumourspheres formation/CSC markers ALDH and CD44 from ascites and ovarian cancer cell lines, compared to monolayer cells/ALDH−CD44− subsets." (PMID 32390009, 2020). "Additionally, some findings indicated that epithelial ovarian cancers may derive from a subpopulation of CD44+CD117+ and that drug-resistant A2780 cells display ovarian CSC properties." (PMID 32245092, 2020). "Whether HGF can induce CD44 expression in ovarian cancer cells needs further study." (PMID 32967712, 2020). "However, it has been shown in ovarian cancer that the prognostic value of CD44 may depend on its isoform, with the transmembrane form indicating a better prognosis, while the presence of the soluble extracellular domain was associated with a worse prognosis." (PMID 32154167, 2020). "Therefore, we consider that the drug delivery targeting CD44 in ovarian cancer could lead to successful results in suppressing specifically CSC population in the tumor site." (PMID 30818864, 2019). "Presumably, CD44 may regulate chemoresistance of ovarian cancer via ZEB1." (PMID 31497537, 2019). "Presumably, CD44 may be a potent therapeutic target of human ovarian cancer." (PMID 31497537, 2019). "Therefore, CD44 may be a potential target for ovarian cancer not only due to its effect on stem cell properties, but also due to its pivotal role in EMT." (PMID 31497537, 2019). "CD44v6 is one of the most common variants of CD44, and some meta-analyses have shown that the expression of CD44v6 is related to a poor prognosis in gastric and hepatocellular carcinomas but is not related to prognosis in ovarian cancer." (PMID 30788285, 2019). "Therefore, CD44 may be a potential prognostic marker as well as treatment target for ovarian cancer." (PMID 31497537, 2019). "Furthermore, CD44 could serve as a promising biomarker to predict the diagnosis and prognosis of patients suffering from ovarian cancer." (PMID 30996686, 2019). "Moreover, this study demonstrated that the small subpopulation of stem-like, tumor-propagating ovarian cancer cells were earmarked by expression of cluster of differentiation 44 (CD44) and other stem cell and EMT markers such as KIT (CD117), SCF (stem cell factor), SLUG (SNAIL2), and VIM (vimentin)." (PMID 31614568, 2019). "Of note, CD44 is a major Wnt target gene in the intestinal epithelium and is essential for Wnt induction during colon cancer progression, thus suggesting yet another functional link between Wnt signaling and ovarian cancer exosomes in pre-metastatic niche formation." (PMID 31614568, 2019). "Furthermore, our in vitro data suggested that CD44 may promote ovarian cancer progression through the EMT process by regulating Snail and ZEB1." (PMID 31497537, 2019). "Thus, CD117+/CD44+ ovarian cancer cells were shown to have a higher basal autophagy than the CD117− counterpart; inhibition of this pathway by cloroquine treatment inhibits the growth and the survival of ovarian cancer spheroids and their tumorigenic activity in vivo." (PMID 29389895, 2018). "These previous studies suggest that PDGF and CD44 may play a role in the biology of ovarian cancer." (PMID 30301218, 2018). "Although the role CD44 expression plays in ovarian cancer recurrence, metastasis, and drug resistance is unknown, the results showing that knockdown of CD44 inhibits tumor cell proliferation and migration/invasion provides evidence that CD44 may directly participate in ovarian cancer progression." (PMID 25823654, 2015). "However, mechanisms that induce expression of CD44 in ovarian cancer are poorly understood." (PMID 26569327, 2015). "Importantly, CD44 has been identified as a “stem cell” marker for both breast and ovarian cancer." (PMID 26299618, 2015).
ovarian carcinoma (continued). "In this study, we tested HA-PEI/HA-PEG CD44 targeted nanoparticle for MDR1 siRNA in ovarian cancer MDR cells with anticipation that this delivery system will result in the lowering of the apoptotic threshold necessary for augmenting the efficacy of paclitaxel in a MDR ovarian cancer model." (PMID 25687880, 2015). "Interestingly in addition to glioblastoma, a similar endothelial potential may be shared by CD44-expressing cells isolated from ovarian cancer." (PMID 26189059, 2015). "Studies on the properties of these “stem” cells in ovarian cancer using an Aldefluor assay to isolate ALDH1-bright (ALDH1br) cells from epithelial ovarian cancer cell lines, revealed greater stem-like properties, an enrichment in CD44, and association with chemoresistance and poor clinical outcome." (PMID 26569327, 2015). "The significance of our findings is the possibility of developing new venues to target the surviving CD44+/MyD88+ EOC stem cells as part of maintenance therapy and therefore preventing recurrence and metastasis, which are the main causes of mortality in patients with ovarian cancer." (PMID 24403249, 2013). "Interestingly, studies reported that CD44+CD24− cells from epithelial human ovarian cancer cell lines have properties of ovarian CSCs/TICs, whereas another study reported that CD24+ cells from ovarian cancer patient samples are a subpopulation of ovarian CSC/TICs." (PMID 23528891, 2013). "Thus, we analyzed CD44 staining in ovarian cancer tissue sections obtained from 117 patients." (PMID 21904548, 2011). "The top two EMT‐related abundant genes in the Dplhi group, serpin family E member 1 (SERPINE1) and CD44, were reported to induce EMT in ovarian cancer." (PMID 41317023, 2026). "This nanotechnological system showed high therapeutic potential for the targeted treatment of ovarian carcinoma with a novel DDS that effectively and simultaneously transports a drug combination containing siRNA targeting CD44 mRNA and cytotoxic agents." (PMID 40142941, 2025). "In CD133+ ovarian cancer cells, LINC00115 silencing decreases the expression of CD44, CD133, and NANOG." (PMID 39967908, 2025). "The increased expression of CD44 and VDR in aggressive ovarian cancer, along with elevated CD133 levels in atypical proliferative tumors, highlights the complexity of tumor biology." (PMID 40332380, 2025). "The selected CD44 X-aptamers (both amine form and ADDA form) also showed enhanced binding affinity to CD44-overexpressing human ovarian cancer IGROV cells." (PMID 40001633, 2025). "A moderate positive correlation was found between CD44, CD133, and VDR in all groups, with significant correlations with tumor grade and FIGO stage in ovarian cancer (p < 0.05)." (PMID 40332380, 2025). "Another study in CaOV-3 and SKOV-3 ovarian cancer cells shows that EGF triggers MAPK/ERK signaling to enhance cell migration, with HA and CD44 involvement in CaOV-3 cells." (PMID 40507943, 2025). "Ovarian cancer, especially HGSC, showed a significantly higher expression of CD44 and VDR (p < 0.05) compared to atypical proliferative tumors and benign tumors." (PMID 40332380, 2025). "In our previous study, we checked the expression of ovarian cancer stemness markers ALDH, CD44, ABCG2, and NANOG and spheroids’ clonogenic nature through PKH staining." (PMID 39596687, 2024). "Exposure to the iron chelator deferoxamine (DFO) significantly reduced the stemness-related transcription factors Nanog and Sox2, mammosphere formation, and the CD44+/CD133+ and ALDH+ SK-OV-3 ovarian cancer cell subpopulations." (PMID 38704599, 2024). "Cell surface receptors, such as human epidermal growth factor 2 (HER2), folic acid (FA) receptors, CD44 (also referred to as homing cell adhesion molecule, HCAM), and vascular endothelial growth factor (VEGF) are highly expressed in ovarian cancer cells." (PMID 39125873, 2024).
ovarian carcinoma (continued). "The overexpression of CD105 with the co-expression of CD44 and CD106 was determined in paclitaxel-resistant ovarian cancer cell lines and primary ovarian cancer cells resistant to different chemotherapeutics." (PMID 38791431, 2024). "DAB2 expression had a significant positive correlation with HA synthesis protein HAS2, HA receptor CD44 and co-receptor toll like receptor 4 (TLR4) in both ovarian cancer cell lines (CCLE) and patient tissues (TCGA: microarray and RNAsequencing data)." (PMID 37815603, 2023). "Firstly, we analyzed the expression of known ovarian cancer stemness markers: ALDH1, CD44, ABCG2, and NANOG." (PMID 37511212, 2023). "An enriched population of cancer stem cells with stemness markers like CD24, CD44, CD117, and CD133 are often found in ovarian cancer spheroids." (PMID 37776168, 2023). "For instance, GW4869, an inhibitor of exosome release, was found to attenuate CD44 expression and reverse EMT in PMCs by inhibiting exosome release in ovarian cancer cells, thereby inhibiting ovarian cancer invasion." (PMID 37215442, 2023). "Some scholars have constructed a prognostic grading model of ovarian cancer containing 5 ferroptosis-related factors (ALOX12, ACACA, SLC7A11, FTH1, and CD44) through biological analysis, which showed great value in the prognostic analysis of this disease." (PMID 37304234, 2023). "DAB2 expression had significant positive correlations with mesenchymal markers (ZEB2, TGFβ1, SNAI2, ZEB1, FN1, MMP2, TWIST1 and MMP3) and CSC markers (CD44 and MYD88) in ovarian cancer cell lines (CCLE) and tissues (TCGA: RNA sequencing and microarray)." (PMID 37815603, 2023). "Unlike most of the published reports showing that several surface markers used to identify ovarian CSCs, such as CD24, CD44, CD117, and CD133, we have unveiled the ACTL6A had poor prognosis and correlated enrichment of CSCs in ovarian cancer." (PMID 36768349, 2023). "We performed an FACS analysis of the commonly used stem cell markers in ovarian cancer (ALDH1A1 and CD44)." (PMID 36375842, 2023). "CD44-positive expression was predominantly correlated with a high TMN and worse 5-year overall survival in ovarian cancers in a meta-analysis of 18 publications including 2,161 patients." (PMID 35464064, 2022). "To study the role of PFKFB3 in altered CSC metabolism in ovarian cancer, we performed metabolic assays using tumorspheres/ALDH+CD44+ cells transfected with siPFKFB3 duplexes and ALDH-CD44- cells transfected with PFKFB3." (PMID 35155224, 2022). "It is associated with the transition of epithelial stem-like Type I/CD44+ EOC cells to mesenchymal Type II/CD44- EOC cells, suggesting that TWIST1 regulates ovarian cancer cell differentiation." (PMID 36123378, 2022). "In ovarian cancer models, it has been reported that FAK inhibition reduces CD44 protein expression levels and stem phenotype." (PMID 35820889, 2022). "First, a large number of literatures suggest that CD44, CD117, CD133, CD24, aldehyde dehydrogenase (ALDH) and other markers can be used to investigate cancer stem cells in certain ovarian cancer types." (PMID 36046821, 2022). "In the present report, we studied the status of membrane fluidity and the level of CD44 in normal ovary epithelium and stage III high-grade serous ovarian cancer (HGSOC), a common epithelial ovarian cancer." (PMID 36789687, 2022). "PIK3R3 expression in ovarian cancer positively correlated with sex determining region Y-box 2 (SOX2), CD44, and aldehyde dehydrogenase 1 (ALDH1A1)." (PMID 35761259, 2022). "In order to further explore the specific role of PEG-MZF-NPs/CD44-shRNA/DDP nanoliposomes, we established a human ovarian cancer xenograft model in nude mice." (PMID 35402279, 2022). "Hence, CD44 might be a conceivable target in ovarian cancer treatment." (PMID 35402279, 2022).
ovarian carcinoma (continued). "Increased expression of CSC markers and transcription factors, such as CD44, KIT Proto-Oncogene (KIT, CD117), POU Class 5 Homebox 1 (POU5F1, OCT4), and NANOG, was observed in ovarian cancer cells treated by cisplatin or paclitaxel both in vitro and in vivo." (PMID 35401749, 2022). "Another third-generation anti CD44+ CAR engineered NK cells showed strong cytotoxic activity against CD44+ ovarian cancer SKOV3 and OVCAR3 cell lines and primary ovarian cancer cells harvested from ascites, compared to CD44-negative A2780 cells." (PMID 35269636, 2022). "Genes significantly downregulated by ALDH1A1 inhibition included stem cell markers (CD44, FZD7, and SOX9) and genes involved in chemoresistance (ABCB1 and NFκB) in ovarian cancer." (PMID 35884498, 2022). "For instance, HA binds to CD44 and triggers the NANOG‐STAT3 pathway activation, leading to the self‐renewal of ovarian cancer cells." (PMID 36226253, 2022). "In future study, we will separate DDP, CD44-SHRNA, and MFH into separate groups in the future study to further clarify the therapeutic efficacy of single treatment regimen for ovarian cancer." (PMID 35402279, 2022). "Making use of PEG-MZF-NPs’ excellent magnetic response and effective temperature control, CD44-shRNA gene therapy, DDP chemotherapy, and magnetic thermotherapy were organically combined together to treat ovarian cancer in vitro and in vivo." (PMID 35402279, 2022). "In one of our previous studies, we constructed CD44-shRNA plasmids and transfected them into ovarian cancer SKOV-3 cells by PEG-MZF-NPs; CD44 gene expression was significantly inhibited, indicating CD44-shRNA has a good potential to treat ovarian cancer." (PMID 35402279, 2022). "Various specific markers (clusters of differentiation), including CD44 and CD133, have been employed for the isolation and characterization of ovarian CSCs from ovarian cancer cell lines and patients’ tumors." (PMID 34769230, 2021). "NK-92 cells equipped with the anti-CD44 CAR exhibited potent cytotoxic activity against CD44-positive ovarian cancer cell lines and primary ovarian cancer cells." (PMID 34680456, 2021). "To delineate the ALDH+CD44+ cells in EOC, we measured the percentage of ALDH+CD44+ cells in MCAs samples from EOC ascites and 3 ovarian cancer cell lines." (PMID 33726845, 2021). "For instance, targeting of CD44 by miRNAs in NSCLC, prostate and ovarian cancer has been demonstrated to attenuate stemness." (PMID 34712602, 2021). "Since CD44NK cells showed activity against all tested cell lines and primary cells that express CD44, we assume that the CD44NK cells will also be effective against other ovarian cancer cells that express CD44." (PMID 34680456, 2021). "While the molecular target of Cantrixil is yet to be confirmed, it has been identified as having potent cytotoxicity against chemoresistant CD44+/MyD88+ ovarian CSC clones and chemosensitive CD44-/MyD88- ovarian cancer cell lines." (PMID 34206826, 2021). "HA/PEI and HA/PEG nanoparticles were used to deliver multidrug resistance 1 (MDR1) siRNA in CD44+ ovarian cancer cells in combination with PTX, resulting in MDR1 downregulation, increasing apoptosis and the suppression of ovarian cancer growth." (PMID 34944493, 2021). "In this study, we developed a novel CD44-specific third-generation CAR and analyzed its anti-tumor activity in ovarian cancer cell lines and primary patient-derived ovarian cancer cells." (PMID 34680456, 2021). "Their flow cytometry assay results pointed to a sixfold improved uptake of the multifunctional nanogel, in CD44- and EGFR-positive SKOV-3 ovarian cancer cells, compared to CD44-NG, as well as to increased cell apoptosis in vitro." (PMID 33981532, 2021). "Remarkably, the expression of standard ovarian cancer CSC markers, such as CD24 and CD44, gradually increases along the EMT trajectory." (PMID 34830900, 2021).
ovarian carcinoma (continued). "Understanding the metabolic characteristics associated with therapy resistance and uncovering the underpinning mechanisms, such as CD44 and STAT3 crosstalk, will provide insight into novel therapeutic interventions to overcome ovarian cancer chemoresistance." (PMID 33335857, 2020). "Relevant to the scope of this review, several studies have demonstrated beneficial effects of combined CD44 and STAT3 signaling downregulation across different cancer models, including ovarian cancer." (PMID 33335857, 2020). "Low doses of metformin have been shown to selectively inhibit CD44+ and CD117+ CSCs in SKOV3 and A2780 ovarian cancer cell lines." (PMID 35582216, 2020). "The expression of the chemotherapy-induced upregulated EMT markers (VIM and Snail) and stem cell markers (CD44 and CD133) in ovarian cancer was also reserved by GLI1 knockdown." (PMID 32242101, 2020). "To determine the effect of HATMSC2 -MVs on the phenotype of ovarian cancer cell lines treated at the ratios of 10:1 and 100:1, we tested the presence of the CD34, CD44, CD133, SSEA4, CD73, CD90, and CD105 markers using flow cytometry." (PMID 33266317, 2020). "Follow-up functional experiments illustrated that inhibiting GLI1 reversed the chemotherapy-exacerbated CSC-like traits, including CD44 and CD133, as well as prevented the migration of ovarian cancer cells." (PMID 32242101, 2020). "Ovarian cancer stem cells (CSCs), also known as cancer-initiating cells, are characterized by cell surface expression of CD24, CD44, CD117 (KIT), SOX2, and NANOG." (PMID 32823589, 2020). "From them, CK19, MUC1, CD24, CD44, TIMP1, and CXCR4 appeared, characterizing the ovarian cancer circulating population." (PMID 32423054, 2020). "More importantly for the scope of this review, tumor-promoting TAMs have been reported to drive ovarian cancer metastasis, stemness, and therapy resistance with the involvement of STAT3 and CD44." (PMID 33335857, 2020). "For instance, twist-related protein 1 (Twist1)-mediated upregulation of miR-199a/214 has been shown to be essential for the transformation of ovarian cancer stem cells (Type I/CD44+) into mature, fast-dividing cancer cells (Type II/CD44−)." (PMID 32850313, 2020). "Well-studied ovarian cancer stem cell biomarkers include aldehyde dehydrogenase (ALDH) and CD44/CD117." (PMID 32180719, 2020). "To ascertain the correlation between PDK4 overexpression and altered CSC properties in ovarian cancer, we generated transient siPDK4-transfected tumourspheres/ALDH+CD44+ cells as well as ALDH−CD44− cells transiently overexpressing PDK4." (PMID 32390009, 2020). "To this end we employed RT-qPCR analysis, western blot and/or immunofluorescence to assess the expression of CD44, NANOG, OCT4 and SOX2, regarded as putative ovarian cancer stem cells markers." (PMID 33250051, 2020). "CD44 is a non-kinase transmembrane receptor that has been linked to cancer metastatic progression, cancer stem cell maintenance, and chemoresistance development via multiple mechanisms across many cancers, including ovarian, and represents a promising therapeutic target for ovarian cancer treatment." (PMID 33335857, 2020). "We demonstrated enhanced CSC characteristics of tumour cells derived from ovarian cancer ascites, concomitant with ALDH and CD44 subset enrichment and high PDK4 expression, compared to primary tumours." (PMID 32390009, 2020). "In the present study, we demonstrated that CD44 expression positively correlated with FIGO stage and histological grade of ovarian cancer." (PMID 31497537, 2019). "The targeting selectivity of the NPs was then explored using two human ovarian cancer cells: SKOV3 that overexpressed CD44, and A2780 cells in which CD44 was undetectable." (PMID 31060303, 2019).